TSLP (thymic stromal lymphopoietin)
Diseases named in the same sentence as TSLP in open-access papers (continued):
Sharing a sentence is not in itself a finding about the gene and the disease.
Granuloma (3 papers, 2022 to 2023). A compact, organized collection of mature mononuclear phagocytes, which may be but is not necessarily accompanied by accessory features such as necrosis. "Cytokines such as IL-1β, IL-4 IL-5, IL-6, IL-13, TNF-α, MCP-1, and TSLP induce allergy-related inflammation, which causes tissue fibrosis, granuloma formation, and leukocyte infiltration." (PMID 36235405, 2022). "In our study, we found TSLP was significantly expressed in the epidermis of sarcoidosis and the dermal epithelioid cells in “naked” granulomas, which implies that TSLP may be secreted by both keratinocytes and epithelioid cells in cutaneous sarcoidosis." (PMID 36046760, 2022).
liver fibrosis (3 papers, 2020 to 2024). "However, another study demonstrated an overlapping role of IL-33, IL-25, and TSLP in a schistosome-induced lung granuloma and liver fibrosis model." (PMID 32132991, 2020). "Moreover, TSLP activates group 2 innate lymphoid cells in the liver, promoting liver fibrosis." (PMID 38919941, 2024). "Hepatic fibrosis induced by S. mansoni is not affected by the lack of TSLP, IL-25, and IL-33 signaling individually, but disruption of signaling by all three mediators reduced hepatic fibrosis, eosinophils, and innate lymphoid cell (ILC)-2 in the liver of mice." (PMID 32922381, 2020).
mastocytosis (3 papers, 2015 to 2025). A clonal myeloproliferative neoplasm characterized by the proliferation and accumulation of neoplastic mast cells in one or multiple organs or organ systems. "Our finding that IL-25 is essential for vaccine-driven effector responses is somewhat surprising because it has been largely considered to be (alongside IL-33 and TSLP) a key inducer cytokine, acting at an early stage to drive ILC2s, mastocytosis and, in turn, Th2 immunity." (PMID 25816012, 2015). "Additionally, Thymic Stromal Lymphopoietin (TSLP) acts together with IL-33 and also activates an abnormal mast cell for tryptase production in mastocytosis." (PMID 39859245, 2025).
Netherton syndrome (3 papers, 2015 to 2024). Netherton syndrome (NS) is a skin disorder characterized by congenital ichthyosiform erythroderma (CIE), a distinctive hair shaft defect (trichorrhexis invaginata; TI) and atopic manifestations. "Induction of AD-like lesions through PAR2-mediated thymic stromal lymphopoietin expression has been demonstrated in Netherton syndrome." (PMID 26717000, 2015).
osteoarthritis (3 papers, 2013 to 2024). A noninflammatory degenerative joint disease occurring chiefly in older persons, characterized by degeneration of the articular cartilage, hypertrophy of bone at the margins and changes in the synovial membrane. "RA patients have higher levels of TSLP in synovial fluids than osteoarthritis patients, and the TSLP receptor is overexpressed in myeloid dendritic cells of synovial fluids in RA patients." (PMID 38512921, 2024). "Recently, increased levels of TSLP in SF of RA patients versus osteoarthritis patients were documented." (PMID 24286358, 2013).
respiratory infections (3 papers, 2020 to 2025). "Multiple factors impact TSLP expression such as environmental exposures (allergens, respiratory infections, air pollution) and host factors (age, gender, BMI, genetic polymorphisms)." (PMID 41357156, 2025).
rosacea (3 papers, 2018 to 2025). A chronic erythematous skin disorder that affects the face. "We demonstrated that keratinocytes exhibited increased protein and gene expression of TSLP when incubated with LL-37 treated MCs, suggesting a correlation with our in vivo observations in a rosacea model." (PMID 41296102, 2025). "The sebum compositions and TSLP expression markedly decreased in the skin lesion of patients with rosacea, while IFN-γ and IL-17 elevated significantly." (PMID 34249003, 2021). "TSLP, a key type 2 cytokine implicated in chronic skin inflammation, has recently been linked to MRGPRX2 activation, which is also associated with the pathogenesis of rosacea." (PMID 41296102, 2025). "However, there are few studies on the specific biological activity of TSLP in the pathogenesis of rosacea." (PMID 34249003, 2021).
systemic lupus erythematosus (3 papers, 2021 to 2022). An autoimmune multi-organ disease typically associated with vasculopathy and autoantibody production. "Recently, pathway-based analyses have suggested that numerous potential pathways, including TSLP signaling, could be involved in the immunopathogenesis of systemic lupus erythematosus (SLE)." (PMID 34249003, 2021).
acid reflux (2 papers, 2022 to 2025). "Background/Objectives: In children, gastroesophageal reflux disease (GERD) may lead to epithelial barrier dysfunction and the release of thymic stromal lymphopoietin (TSLP), interleukin-25 (IL-25), interleukin-33 (IL-33) and periostin, known as alarmins." (PMID 40981017, 2025).
actinic keratosis (2 papers, 2020 to 2022). A precancerous lesion of the skin composed of atypical keratinocytes. "On the opposite side, treatment with calcipotriol, which increases TSLP levels, in combination with 5-fluorouracil was superior to combination with Vaseline in reducing actinic keratosis lesions." (PMID 33042121, 2020).
acute myocardial infarction (2 papers, 2022 to 2024). Necrosis of the myocardium, as a result of interruption of the blood supply to the area. "However, the effect of plasma TSLP level after acute myocardial infarction (AMI) remains largely unclear." (PMID 35321112, 2022).
adult onset asthma (2 papers, 2015 to 2020). "Thymic stromal lymphopoietin (TSLP) is one possible mediator of smoking-induced adult-onset asthma; it was elevated in the sputum of smokers with adult-onset asthma, positively correlated with pack-years and negatively correlated with FEV1/FVC." (PMID 26538828, 2015). "A singular GWAS study of a Japanese adult-onset asthma population showed that SNPs of HLA-, thymic stromal lymphopoietin-WD repeat domain 36 (TSLP-WDR36)-, and ubiquitin specific peptidase 38-GRB2 associated binding protein 1 (USP38-GAB1) loci are associated with adult-onset asthma." (PMID 32292784, 2020).
anaphylaxis (2 papers, 2017 to 2025). An acute hypersensitivity reaction that occurs from exposure to an allergen. "Using the codominant model, the OR associated with TSLP SNP was estimated at 3.94 (95%CI 1.34 ÷ 11.6) for AD combined with FA, at 4.89 (95%CI 1.48 ÷ 16.1) for AD combined with anaphylaxis, and at 4.85 (95%CI 1.55 ÷ 5.18) for patients with FA and anaphylaxis." (PMID 39860604, 2025). "Statistically, highly significant increases in serum TSLP and IL-1β levels were also observed in individuals with multiple allergic conditions (AD + FA, AD + anaphylaxis, FA + anaphylaxis, and AD + FA + anaphylaxis)." (PMID 39860604, 2025). "The study findings indicate that the serum levels of TSLP and IL-1β were significantly elevated in patients with AD, FA, and anaphylaxis, as well as in individuals with multiple allergic conditions." (PMID 39860604, 2025). "This suggests that it is unlikely that basophil migration during anaphylaxis is related to changes in basophil development or homeostasis, a process that is IL-3 elicited for basophils that operate in an IgE-dependent manner or TSLP elicited for basophils that operate in a non–IgE-dependent manner." (PMID 28342911, 2017).
chronic GVHD (2 papers, 2021 to 2023). "Differential expression analysis showed that low levels of IL18-R1, LIF-R and IL22-RA1 were seen in patients who subsequently developed acute graft versus host disease (AGvHD) whilst lower levels of CD244, TSLP, IL15-RA and IL-33 were observed in patients who developed chronic GvHD." (PMID 38235129, 2023).
colorectal adenocarcinoma (2 papers, 2019 to 2025). The most common type of colorectal carcinoma. "These immortalized human colorectal adenocarcinoma cells secrete key inflammatory mediators, such as IL-6, IL-8, IL-15, TNF-α, and thymic stromal lymphopoietin (TSLP), making them valuable for inflammation-related assays in IBD research." (PMID 41155651, 2025).
Coronary Artery Disease (2 papers, 2018 to 2025). "The thymic stromal lymphopoietin (TSLP)/TSLP receptor (TSLPR) axis is involved in multiple inflammatory immune diseases, including coronary artery disease (CAD)." (PMID 30123216, 2018).
Dry skin (2 papers, 2021). Skin characterized by the lack of natural or normal moisture. "Previous studies have demonstrated that protease-activated receptor 2 (PAR2), TRPV3, and TRPV4, are involved in the production of TSLP in keratinocytes under dry skin conditions." (PMID 34925342, 2021).
emphysema (2 papers, 2018 to 2025). "Biologics targeting upstream alarmins (e.g., IL-33/TSLP) and downstream cytokines (e.g., IL-1β, IL-6) aim to disrupt inflammatory redundancy; cell-based and regenerative approaches represent long-term precision strategies for emphysema." (PMID 41024111, 2025).
eosinophilic diseases (2 papers, 2017 to 2024). "Our characterization of TSLP in these mice was particularly rewarding given the importance of TSLP in both EoE and eosinophilic diseases as a whole." (PMID 29259025, 2017).
fungal keratitis (2 papers, 2021 to 2022). "The thymic stromal lymphopoietin (TSLP) in fungal keratitis and the infection of Middle East respiratory syndrome coronavirus (MERS-CoV) also showed similar effects to induce pyroptosis of THP-1 macrophages." (PMID 35415237, 2022). "TSLP induces caspase-1–dependent pyroptosis through activation of the NLRP3 inflammasome, suggesting that it may be a potential target for fungal keratitis." (PMID 34925047, 2021).
lung adenocarcinoma (2 papers, 2021 to 2022). A carcinoma that arises from the lung and is characterized by the presence of malignant glandular epithelial cells. "In this report, we have shown that TSLP cytokine induction can mount a strong antitumor immunity in an oncogene-driven in vivo model of spontaneous lung adenocarcinoma." (PMID 35565302, 2022). "In conclusion, we have shown that TSLP induction reduces tumor burden and blocks cancer progression in a mouse model of spontaneous lung adenocarcinoma." (PMID 35565302, 2022). "Using a mouse model of lung adenocarcinoma, we investigated the effects of thymic stromal lymphopoietin (TSLP) induction on early cancer development in the lungs." (PMID 35565302, 2022). "To determine the effects of TSLP induction on early carcinogenesis in the lung, we crossed a mouse model of spontaneous lung adenocarcinoma, Kras+/G12D (KrasG12D), with K14-TSLPtg (Tslptg) mice." (PMID 35565302, 2022). "Accordingly, we hypothesize that TSLP induction in patients with early lung adenocarcinoma may prevent cancer progression and recurrence." (PMID 35565302, 2022).
lung injury (2 papers, 2020 to 2025). "In this study, we investigated that TSLP pretreatment on macrophage infiltration and polarization of M1 macrophages in LPS- induced acute lung injury." (PMID 40486522, 2025).
lymphedema (2 papers, 2021 to 2026). Excess fluid collection in tissues, causing swelling. "Deficiency of PAR2 or topical inhibition of thymic stromal lymphopoietin rescues secondary lymphedema by reducing Th2 inflammation." (PMID 42226615, 2026). "Our study’s findings suggest that TSLP may also be a target for lymphedema treatment and that additional studies are warranted." (PMID 34571811, 2021). "Interestingly, we found that patients with lymphedema have significantly increased expression of Th2-inducing cytokines (TSLP, IL33, IL25) in the epidermal cells of the lymphedematous limb, and that treatment with QBX258 decreased or normalized these changes." (PMID 34571811, 2021).
lymphopenia (2 papers, 2013 to 2021). Reduction in the number of lymphocytes. "Expression of the activation marker HLA-DR correlated with TSLP responses, suggesting that lymphopenia-driven immune activation increased the sensitivity of CD4+ T cells to TSLP." (PMID 23383227, 2013).
metastatic disease (2 papers, 2020 to 2024). "Experiments in TSLP KO mice then showed that TSLP signaling was required for metastatic disease progression to the lung." (PMID 33042121, 2020).
occupational asthma (2 papers, 2023). Asthma attacks caused, triggered, or exacerbated by OCCUPATIONAL EXPOSURE. "In the occupational asthma mouse model induced by toluene-diisocyanate, Th17 cell differentiation and IL-17 secretion are inhibited by intraperitoneally administered TSLP-Ab." (PMID 36834541, 2023).
oral lichen planus (2 papers, 2017 to 2020). Oral lichen planus is a chronic inflammatory oral condition of unknown aetiology characterized by T-cell-mediated chronic immune response and abnormal epithelial keratinization cycle. "Other authors demonstrated that increased periostin expression in the oral mucosa and serum of patients with oral lichen planus (OLP) was associated with inflammatory response, where Th2 cytokine was predominant in immune imbalance and elevated TSLP concentrations." (PMID 33203095, 2020).
oropharyngeal squamous cell carcinoma (2 papers, 2020 to 2022). "Finally, analyses of surgical specimens of oropharyngeal squamous cell carcinoma indicated that high IFN-γ and low IL-4, low TSLP, and low TGFβ expression was associated with better prognosis in oropharyngeal squamous cell carcinoma patients." (PMID 33042121, 2020).
papilloma (2 papers, 2014 to 2020). A benign epithelial neoplasm that projects above the surrounding epithelial surface and consists of villous or arborescent outgrowths of fibrovascular stroma. "Consistent with this, TPA-treated EPI−/− skin produced higher levels of TSLP than WT skin, and was protected from chemically induced papilloma formation." (PMID 24843010, 2014). "In addition, EPI−/− mice bearing papillomas larger than 2 mm2 had higher levels of systemic TSLP than EPI−/− mice with smaller papillomas." (PMID 24843010, 2014).
peanut allergy (2 papers, 2022 to 2023). "However, the secretion of proinflammatory factors and TSLP gene expression in mice treated with enzyme-treated peanut significantly decreased, indicating that enzyme treatment can effectively ameliorate the phenomenon of peanut allergy." (PMID 37444372, 2023). "Murine studies revealed that increased epithelial IL33 secretion is sufficient for in vivo DC activation leading to peanut allergy, independent of IL25 and TSLP." (PMID 36700233, 2022).
polyp (2 papers, 2016 to 2025). A usually exophytic mass attached to the underlying tissue by a broad base or a thin stalk. "Similarly, the expression of TSLP observed in biopsy samples was statistically significantly elevated in the polyp tissue of the patient compared with healthy controls." (PMID 39940994, 2025). "This enhanced induction of TSLP may be a consequence of a down-regulated expression of DUSP-1 in polyp epithelium." (PMID 27050744, 2016). "The enhanced production rate of TSLP after poly(I:C) challenge is TSLP-specific, as we could not detect any statistical differences for IL-8 in response to these (and other) triggers between polyp or healthy nasal epithelium." (PMID 27050744, 2016).
Respiratory syncytial virus infection (2 papers, 2016 to 2019). "ILC2 cells also express the receptor for TSLP, and together with IL-25 and IL-33, TSLP has been shown to induce ILC2s following rhinovirus and respiratory syncytial virus infection." (PMID 31354734, 2019).
sarcoidosis (2 papers, 2017 to 2022). Sarcoidosis is a multisystemic disorder of unknown cause characterized by the formation of immune granulomas in involved organs. "Besides, TSLP expression in the stratum spinosum is significantly higher than that in the stratum basale of LP specimens and significantly lower than that in sarcoidosis specimens." (PMID 36046760, 2022). "Finally, we found positive TSLP staining in the dermal infiltrating inflammatory cells in BP, PsV, and sarcoidosis." (PMID 36046760, 2022). "In sarcoidosis, TSLP was expressed in epithelioid cells in “naked” granulomas." (PMID 36046760, 2022). "In addition, we found that TSLP was also expressed in the dermal infiltrating inflammation cells in BP, PsV, and sarcoidosis." (PMID 36046760, 2022). "Moreover, we found positive TSLP staining in the dermal infiltrating inflammatory cells of BP, PsV, and sarcoidosis." (PMID 36046760, 2022). "It remains to be elucidated if TSLP plays a role in some inflammatory diseases, such as DLE and sarcoidosis." (PMID 36046760, 2022). "TSLP was detected in 23 of 40 NCs, 100 of 100 patients with IPF, 18 of 22 patients with NSIP, 18 of 20 patients with HP, and 18 of 19 patients with sarcoidosis." (PMID 28202030, 2017). "The TSLP and IL-33 levels were significantly higher in patients with IPF relative to the NCs (p = 0.01 and p = 0.0001, respectively), NSIP (p = 4.95E − 7 and p = 0.0002, respectively), HP (p = 0.00003 and p = 0.000005, respectively), and sarcoidosis groups (p = 0.003 and p = 0.0001, respectively)." (PMID 28202030, 2017).
skin sensitization (2 papers, 2013 to 2020). An immunological response to previous exposure to a substance which results in an inflammatory skin reaction. "As expected, TSLP production in the skin was increased 24 h following DBP-FITC skin sensitization." (PMID 32508831, 2020). "The TSLP−/− mice used in the present study were recently utilized in a skin sensitization model for examining pulmonary responses and the findings in this latter study also suggested that TSLP was dispensable for airway challenge at later time points after skin sensitization." (PMID 23437132, 2013).
squamous carcinoma (2 papers, 2015 to 2021). "Since this result was not validated at the protein level and the expression of the long or short form of TSLP was not addressed, we tested SSC-25 and several other human squamous carcinoma cell lines (SCC-4, SCC-9, SCC-25, CAL-27) for calcipotriol responsiveness." (PMID 25866638, 2015). "Moreover, our data from squamous carcinoma cell lines showed absence of TSLP upregulation after VD3 stimulation, indicating that neither our data nor published data show that the long form of TSLP mRNA is responsive to VD3 in human skin." (PMID 25866638, 2015).
viral respiratory tract infection (2 papers, 2016 to 2020). A respiratory tract infection caused by a virus. "Collectively, these data demonstrate the importance of ILC2s and TSLP during the early stages of RSV infection and are the first to link TSLP to the activation of ILC2s during a viral respiratory tract infection." (PMID 27156176, 2016). "TSLP has not previously been recognized to affect ILC2s during viral respiratory tract infection; however, it is a known stimulus of ILC2s in other disease models and can be released from epithelial cells in a fashion to IL-33 and IL-25." (PMID 27156176, 2016).
vitiligo (2 papers, 2015 to 2021). Generalized well circumscribed patches of leukoderma that are generally distributed over symmetric body locations and is due to autoimmune destruction of melanocytes. "Further studies also provide robust evidence of a significant genetic association between vitiligo and TSLP." (PMID 34249003, 2021). "An increased vitiligo susceptibility is linked with specific variants of TSLP identified by genetic studies." (PMID 34249003, 2021). "In Korean patients, the TSLP-847C>T polymorphism was lower in vitiligo patients." (PMID 34249003, 2021). "The promoter activity of TSLP-847C decreased dramatically compared to TSLP-847T, which may enhance vitiligo susceptibility through decreased TSLP mRNA expression level, enhanced Th1 responses, and reduced Th2 activity." (PMID 34249003, 2021). "TSLP polymorphisms may be essential genetic predispositions in vitiligo." (PMID 34249003, 2021). "Nonetheless, the expressions of TSLP at the protein levels in serum and lesional skin of patients with vitiligo have yet to be elucidated." (PMID 34249003, 2021). "A case-control study was recently conducted to clarify the relationship between vitiligo and TSLP mRNA expression." (PMID 34249003, 2021).